KL (klotho)
Diseases named in the same sentence as KL in open-access papers (continued):
Sharing a sentence is not in itself a finding about the gene and the disease.
atherosclerosis (continued). "The ROC curve analysis was used to determine the ability of the serum and PBCs gene expression levels of Klotho to distinguish between subjects according to the presence of subclinical atherosclerosis." (PMID 34354161, 2021). "Previous studies have shown that Klotho knockout mice exhibit increased incidence of aging-related diseases including atherosclerosis, vascular and tissue calcification, and CKD." (PMID 33687326, 2021). "Certainly, more studies are necessary to confirm the potential interaction between oxidized LDL, Klotho, Wnt, and atherosclerosis progression." (PMID 32188018, 2020). "The chronically high concentration of pro-inflammatory cytokines like IL6 and TNFα found in atherosclerosis and T2D attenuates renal and vascular Klotho expression by increasing FGF23 concentration through the NF-κB pathway." (PMID 33322009, 2020). "Several studies have provided evidence that Klotho can suppress oxidative stress and inflammation, central processes firmly established in the development of vascular dysfunction, calcification and atherosclerosis." (PMID 31546756, 2019). "Klotho knock-out mice develop striking vascular disease, including widespread vascular calcification, endothelial dysfunction and progressive atherosclerosis together with severe hypervitaminosis D, hypercalcemia and hyperphosophatemia." (PMID 31546756, 2019). "Klotho knockout mice develop a syndrome similar to premature aging, with shortened life span, hyperphosphatemia, atherosclerosis and extensive vascular calcification." (PMID 31185930, 2019). "Klotho has been recently evaluated in atherosclerosis and is assumed to be an age-regulating protein." (PMID 30547758, 2018). "This study provides the experimental evidence supporting the clinical application of Klotho to prevent or treat atherosclerosis." (PMID 28407763, 2017). "Klotho mutant mice display a phenotype characterized by accelerated aging, atherosclerosis, osteoporosis, and lung obstructive disease." (PMID 28912623, 2017). "As apoptosis is a crucial event in atherosclerosis 23, we assessed the effects of soluble klotho against AngII‐mediated apoptosis in HASMC." (PMID 27696667, 2017). "Klotho, an anti-aging protein, has been reported to protect against atherosclerosis and ameliorate endothelial dysfunction in vivo." (PMID 28407763, 2017). "To investigate the involvement of klotho reduction in atherosclerosis, we isolated PBMCs from patients with artery atherosclerosis and examined the mRNA level of klotho using a regular PCR." (PMID 27034587, 2016). "In agreement with in vitro data, a marked reduction of klotho mRNA expression was found in isolated peripheral blood mononuclear cells (PBMCs) from patients with atherosclerosis." (PMID 27034587, 2016). "The findings not only increased our understanding on the protective property of statins in cardiovascular system but also suggested some potential in treating atherosclerosis by targeting klotho." (PMID 27034587, 2016). "Klotho knockout mice exhibit multiple aging-like phenotypes, including atherosclerosis, osteoporosis, emphysema and infertility." (PMID 24386260, 2013). "There were significant decreases in serum Klotho in patients with arterial stiffness defined as baPWV≥1400 cm/sec, atherosclerosis defined as maximum IMT≥1.1 mm and vascular calcification scores of ACI>0%." (PMID 23431388, 2013). "HMG-CoA reductase inhibition enhances the Klotho protein expression in the kidneys and inhibits atherosclerosis in rats with chronic blockade of nitric oxide synthase." (PMID 23431388, 2013). "Klotho gene delivery, mediated by adenoviral vector, in a rat model of atherosclerosis, increased endothelium-dependent NO synthesis and prevented adverse vascular remodelling." (PMID 22121479, 2012). "In our observations, s.Klotho strongly predicted atherosclerosis (especially in Grade 4)." (PMID 39544340, 2024). "Furthermore, there are studies dealing with Klotho and cardiovascular diseases, e.g., atherosclerosis." (PMID 38787156, 2024).
atherosclerosis (continued). "Klotho inhibits several factors that contribute to atherosclerosis." (PMID 39272986, 2024). "Klotho deficiency was shown to cause endothelial dysfunction and arterial stiffening, as well as HTN and impaired angiogenesis, and may be a predictor of atherosclerosis in humans." (PMID 38256639, 2024). "Moreover, Klotho preserves endothelial function and prevents atherosclerosis by inhibiting vascular inflammation and oxidative stress." (PMID 38501099, 2024). "Moreover, the administration of 1,25(OH)2D3 has been shown to elevate the expression of Klotho protein, which protects against age-related ailments such as atherosclerosis, osteopenia, and skin atrophy." (PMID 38276294, 2023). "The association between low Klotho and CVD has been recently extended to PBCCs, in which reductions in Klotho expression have been related with aging process and with the development of pathologies with an inflammatory component, including atherosclerosis." (PMID 37274332, 2023). "Circulating Klotho may participate in vascular health by protecting against endothelial dysfunction which plays an important role in the development of atherosclerosis." (PMID 37274332, 2023). "In the clinical scenario, the reduction in circulating Klotho has been proposed as a predictor of atherosclerosis being related with carotid artery intima-media thickness (CIMT) burden, a marker of subclinical atherosclerosis, as well as with an increased incidence of cardiovascular disease (CVD)." (PMID 37274332, 2023). "FGF 23 was confirmed to be a major contributor to left ventricular hypertrophy through a klotho-independent pathway, but its relation to atherosclerosis, endothelial dysfunction, and vascular calcifications is questionable, especially at the early stages of CKD." (PMID 37043155, 2023). "A protective effect of Klotho on atherosclerosis and ED has been also demonstrated." (PMID 36829843, 2023). "Low levels of Klotho are related to increased mortality and morbidity associated with CVD Animal studies have shown that mice with low levels of s-Klotho had endothelial dysfunction, atherosclerosis, accelerated arteriosclerosis and defects of angiogenesis." (PMID 35055149, 2022). "Thus, they proposed that lower serum Klotho levels was a novel identified predictor of atherosclerosis." (PMID 35197934, 2022). "Lack of Klotho in murine models causes accelerated aging syndrome, atherosclerosis, vascular calcifications, defects in angiogenesis and endothelial dysfunction." (PMID 35307922, 2022). "Furthermore, polymorphisms of Klotho gene have been associated with HDL and LDL cholesterol levels, connecting it with the development of atherosclerosis." (PMID 34603200, 2021). "As in a subgroup of T1D patients with lower levels of Klotho, CIMT and EFT values were higher, whereas LVLGS and FMD percentages were lower, it was concluded that Klotho may have protective effects against atherosclerosis." (PMID 34603200, 2021). "Studies should investigate whether Klotho-regulated autophagy also plays a role in other aging-related diseases such as osteoporosis, atherosclerosis, heart disease and stroke." (PMID 34737707, 2021). "It would be interesting to further explore whether Klotho plays a role in dysfunctional autophagy in Atherosclerosis." (PMID 34737707, 2021). "Regarding subclinical atherosclerosis markers, both serum and PBCs mRNA Klotho levels were positively correlated with ABI (r = 0.556, P < 0.0001 and r = 0.373, P < 0.0001, respectively) and inversely correlated with CIMT (r = − 0.541, P < 0.0001 and r = − 0.437, P < 0.0001, respectively)." (PMID 34354161, 2021). "Whether reduction in serum and PBCs gene expression levels of Klotho directly promote or favor the progression of atherosclerosis in CKD is an intriguing question that requires further study." (PMID 34354161, 2021). "Interestingly, similar to the up-regulation of ox-LDL, decrease inserum Klotho is also reported as a predictor of atherosclerosis." (PMID 28407763, 2017).
atherosclerosis (continued). "Therefore, we inferred that Klotho protects the vascular endothelium through attenuating oxLDL-induced oxidative stress and prevents the development of atherosclerosis." (PMID 28407763, 2017). "As AngII induces senescence of VSMC and accelerates the development of atherosclerosis 7, we investigated whether soluble klotho prevents AngII‐mediated HASMC senescence." (PMID 27696667, 2017). "KL may function as part of a signaling pathway that regulates morbidity in age-related diseases such as atherosclerosis and cardiovascular disease, and mineral metabolism diseases such as ectopic calcification." (PMID 27478698, 2016). "Thus, KLOTHO appears to protect endothelial cells from the inflammatory process, suppressing the development of atherosclerosis in the vascular system." (PMID 25961830, 2015). "Since the decline in soluble Klotho levels represents a negative event occurring in the early stages of cardiovascular-renal disease, Klotho might be considered as a useful biomarker that predicts atherosclerosis and vascular calcification." (PMID 22121479, 2012). "Likewise, a correlation was seen between plasma Klotho and atherosclerosis." (PMID 40119098, 2025). "Further research is needed to determine if the increase in klotho levels among patients undergoing a CR program after an ACS results in improved functional capacity or plays a beneficial pathophysiological role in the atherosclerosis process with improvement of the patient’s prognosis." (PMID 38541889, 2024). "Thus, lower serum levels of Klotho should be considered as an early predictor of atherosclerosis." (PMID 35055149, 2022). "This suggests that reduced serum Klotho may be an early predictor of subclinical atherosclerosis." (PMID 36362692, 2022). "Comparing wild-type VSMCs from an ApoE model of atherosclerosis with a flox’d Pink1 knockout of inducible mitochondrial dysfunction we show WT Pink1 is essential for normal cell viability, while Klotho mediates energetic switching which may preserve cell survival." (PMID 35008643, 2021). "Receiver operating characteristic analysis pointed to the utility of serum Klotho (area under the curve [AUC]: 0.817, 95% CI: 0.736–0.898, P < 0.001) and its gene expression in PBCs (AUC: 0.742, 95% CI: 0.647–0.836, P < 0.001) to distinguish subclinical atherosclerosis." (PMID 34354161, 2021). "Treatment with recombinant Klotho in the field of cardiovascular diseases and the research and development of drugs that regulate signaling pathways may provide novel strategies for the prevention and treatment of atherosclerosis." (PMID 32138681, 2020). "Thus, lower levels of serum Klotho should be considered as an early predictor of atherosclerosis." (PMID 30671457, 2018). "To address this hypothesis, we measured the serum Klotho levels and extensively investigated the relationship between the serum Klotho level and signs of vascular dysfunction, including endothelial dysfunction, arterial stiffness, atherosclerosis and vascular calcification, in CKD patients." (PMID 23431388, 2013). "In addition, circulating klotho maintains endothelial integrity and protects against vascular permeability, preventing medial hypertrophy and perivascular fibrosis.Consequently, disruption of klotho expression is involved in atherosclerosis as well as in other multiple aging phenotypes." (PMID 38541889, 2024). "Klotho, a protein that exists in two forms, membrane-bound Klotho and soluble Klotho, and acts as co-receptor for fibroblast growth factor 23 (FGF23), has been shown to be involved in atherosclerosis and cardiovascular disease." (PMID 37061530, 2023). "In addition to secondary hyperparathyroidism, FGF23 excess and Klotho deficiency have been recognized as novel factors contributing to vascular calcification which might in part explain the link between CKD progression and atherosclerosis." (PMID 27756244, 2016).
atherosclerosis (continued). "klotho protein is capable of participating in and influencing lipid metabolism, and elevated blood lipids (particularly the increase of LDL) constitute a crucial factor for atherosclerosis and cerebral artery stenosis, which subsequently give rise to stroke." (PMID 40452763, 2025). "A similar effect has been observed in patients with elevated Klotho protein level through NF-κB/ERK signaling, with Klotho overexpression in CKD-atherosclerosis models stabilizes plaques and lowers plasma cholesterol and triglycerides via macrophage ER stress pathways." (PMID 41303567, 2025). "Both Klotho protein forms can act as the obligate co-receptor FGF2322, a relatively new member of the fibroblast growth factor family, and has been shown to play a role in the development of atherosclerosis and cardiovascular disease." (PMID 37061530, 2023). "Therefore, Klotho has been suggested as a master regulator of CVD, with a potential role in the pathogenesis of atherosclerosis in CKD patients." (PMID 34354161, 2021). "Circulating Klotho levels and Klotho expression in peripheral mononuclear blood cells were significantly lower in individuals with atherosclerosis than in those without it." (PMID 34737707, 2021). "In this study, we show that CKD patients with subclinical atherosclerosis present reduced levels of serum and mRNA expression in PBCs of Klotho as compared with CKD patients without this clinical status." (PMID 34354161, 2021). "Mice lacking the Klotho gene develop an aging-like phenotype similar to premature human aging, including endothelial dysfunction, vascular calcification, progressive atherosclerosis and myocardial hypertrophy of the cardiovascular system." (PMID 31546756, 2019). "As a result, lack of Klotho in mice results in accelerated aging and development of age-related systemic disorders, such as atherosclerosis." (PMID 24386260, 2013). "The serum Klotho level was a significant determinant of arterial stiffness, but not endothelial dysfunction, atherosclerosis or vascular calcification, in the multivariate analysis in either metabolic model, the CKD model or the CKD-MBD model." (PMID 23431388, 2013). "However, studies about the relationship between Klotho and CIMT in patients with atherosclerosis and preserved kidney function are scarce and none of them had previously considered the expression levels of Klotho in PBCCs and atherosclerotic vascular tissue." (PMID 37274332, 2023). "Klotho treatment may decrease lectin-like oxidized low-density lipoprotein receptor-1 (LOX-1) expression in endothelial cells, which plays a critical role in atherosclerosis development." (PMID 35509269, 2022). "However, studies about the relationship between Klotho and markers of subclinical atherosclerosis in CKD patients are scarce and none of them have considered the expression of Klotho in PBCs." (PMID 34354161, 2021). "Based on these data, we speculate that Klotho protects against ox-LDL-induced endothelial dysfunction partly through suppressing ROS over production, thus inhibiting the initiation and progression of atherosclerosis." (PMID 28407763, 2017). "Patients with atherosclerotic vascular disease showed a non‐significant trend towards lower vascular Klotho mRNA levels as compared with subjects without atherosclerosis: Log a.u. in atherosclerotic patients, 0.41 ± 0.11 versus non‐atherosclerotic patients, 0.82 ± 0.24 (P = 0.11)." (PMID 26538295, 2016). "Thus, a decreased renal Klotho expression was reported in an experimental model of accelerated atherosclerosis in mice with CKD; but the intrinsic factors regulating Klotho in this pathological condition are unknown." (PMID 24386260, 2013). "Moreover, we did not analyze the effect of confounders other than serum Klotho levels as potential predictors of atherosclerosis Specifically, UAE has been previously related with subclinical atherosclerosis, so we cannot exclude the contribution of albuminuria to CIMT values in our study." (PMID 37274332, 2023).
atherosclerosis (continued). "Klotho suppressed the expression of TNF α-induced ICAM1 and VCAM1 adhesion molecules and also inhibited TNF- α induced NF-κB activation and IkB phosphorylation—mechanisms involved in inflammation and atherosclerosis, suggesting that Klotho may play a role in mediating endothelial inflammation." (PMID 35055149, 2022).